NUCB2 (nucleobindin 2)
Description:
Calcium-binding protein which may have a role in calcium homeostasis (By similarity). Acts as a non-receptor guanine nucleotide exchange factor which binds to and activates guanine nucleotide-binding protein (G protein) alpha subunit GNAI3 (By similarity). [Nesfatin-1]: Anorexigenic peptide, seems to play an important role in hypothalamic pathways regulating food intake and energy homeostasis, acting in a leptin-independent manner. May also exert hypertensive roles and modulate blood pressure through directly acting on peripheral arterial resistance. In intestinal epithelial cells, plays a role in the inhibition of hepatic glucose production via MC4R receptor leading to increased cyclic adenosine monophosphate (cAMP) levels and glucagon-like peptide 1 (GLP-1) secretion.
Synonyms: NEFA; HEL-S-109
Tractability: Antibody: UniProt places it where antibodies can reach, with high confidence; its Gene Ontology location is reachable by antibodies, with high confidence; UniProt predicts a signal peptide or a membrane-spanning region. PROTAC: ubiquitination databases record sites on it; its protein half-life has been measured.
Gene: Protein-coding gene on chromosome 11 (17,208,072 to 17,349,980, forward strand). Ensembl gene ENSG00000070081.
Subcellular location: Golgi apparatus; Membrane; Cytoplasm; Secreted; Endoplasmic reticulum; Nucleus envelope; Secreted (Nesfatin-1)
Subcellular location (Human Protein Atlas): Golgi apparatus; Predicted to be secreted
Gene Ontology:
Molecular function: calcium ion binding; protein binding; DNA binding; G-protein alpha-subunit binding; guanyl-nucleotide exchange factor activity
Biological process: small GTPase-mediated signal transduction
Cellular component: endoplasmic reticulum-Golgi intermediate compartment; extracellular exosome; extracellular region; Golgi apparatus; cytosol; plasma membrane; cytoplasm; endomembrane system; endoplasmic reticulum; membrane; nuclear envelope
Genetic constraint (gnomAD): Loss-of-function variants: 5 observed, 8.36 expected, observed/expected ratio (o/e) 0.6, 90% interval 0.31 to 1.25. That is too few expected variants to judge how well the gene tolerates losing a copy. Missense variants: 75 observed, 91.99 expected, observed/expected ratio (o/e) 0.82, 90% interval 0.68 to 0.99. Synonymous variants: 31 observed, 32.44 expected, observed/expected ratio (o/e) 0.96, 90% interval 0.72 to 1.29.
Homologues: Orthologues: chimpanzee NUCB2 (100% identical), macaque NUCB2 (99% identical), rabbit NUCB2 (93% identical), dog NUCB2 (93% identical), guinea pig NUCB2 (93% identical), rat Nucb2 (87% identical), mouse Nucb2 (86% identical), tropical clawed frog nucb2 (71% identical), zebrafish nucb2a (67% identical), zebrafish nucb2b (65% identical), Drosophila melanogaster NUCB1 (41% identical), Caenorhabditis elegans nucb-1 (34% identical). Paralogues in human: NUCB1 (61% identical).
Diseases named in the same sentence as NUCB2 in open-access papers:
NUCB2 is named in the same sentence as 180 diseases in open-access papers, as found by Europe PMC text mining. Sharing a sentence is not in itself a finding about the gene and the disease. The quoted sentences say what the papers report.
Obesity (55 papers, 2013 to 2025). Accumulation of substantial excess body fat. "Background and Objectives: The NUCB2 gene and its polymorphisms were identified as novel players in the regulation of food intake, potentially leading to obesity (OBE) and altered eating behaviors." (PMID 38398053, 2024). "In order to estimate the link between obesity development and nesfatin-1 levels, polymorphisms of NUCB2/nesfatin-1 and the Fat mass and obesity gene (FTO) were also assessed." (PMID 36678225, 2023). "Based on collective data, NUCB2/nesfatin-1 with its associated regulatory processes are recognized as promising targets for treating type 2 diabetes, obesity and metabolic syndrome." (PMID 35386592, 2022). "A recent study performed in a population of 1049 obese Caucasian subjects indicated an association of three single nucleotide polymorphisms (SNPs) (rs1330, rs214101 and rs757081) in the NUCB2 gene with obesity." (PMID 28533821, 2017). "Two of these DW genes have previously been reported to be associated with obesity and diabetes, respectively: the NUCB2 gene and the BCL11A gene." (PMID 25071839, 2014). "Polymorphisms in the NUCB2 gene have been associated with susceptibility to obesity." (PMID 36678225, 2023). "The polymorphisms or mutations of the nesfatin gene, NUCB2, might be associated with the development of obesity." (PMID 34068679, 2021). "Recently, the c.1012C>G polymorphism of NUCB2 gene was found to be correlated with obesity." (PMID 28533821, 2017). "Additionally, two studies have found polymorphisms in NUCB2, the gene for the nesfatin-1 precursor protein, associated with obesity." (PMID 28105016, 2016). "Altered levels of NUCB2/nesfatin-1 have been observed in obesity-related conditions in the rodent hypothalamus and human blood." (PMID 37754352, 2023). "In this regard, many studies have, in fact, tried to explain the link between the NUCB2/nesfatin-1 gene and the development of obesity." (PMID 36678225, 2023). "These pleiotropic actions together with the present findings render the NUCB2/nesfatin-1 system an appealing target for the development of novel therapeutical treatments towards obesity." (PMID 32353862, 2020). "Based on these findings, the modulation of gastric Nucb2/nesfatin-1 has been proposed as a promising therapy for the treatment of obesity." (PMID 32784967, 2020). "Nutrient dependent changes in endogenous NUCB2/nesfatin-1 should also be considered, especially when developing diet or exogenous nesfatin-1 based potential therapies for obesity and related metabolic diseases." (PMID 25506938, 2014). "We aimed to investigate nesfatin-1 secretion in vitro, in murine adipose cells, and in human adipose fat samples, as well as to assess the link between circulating nesfatin-1 levels, NUCB2 and Fat Mass and Obesity Gene (FTO) polymorphisms, BMI, Eating Disorders (EDs), and pathological behaviors." (PMID 36678225, 2023). "The therapeutic potential of NUCB2/nesfatin-1 was discussed in several review articles, especially in the light of its leptin-independent signaling pathway, a hormone known to be less active under conditions of obesity (also known as leptin resistance)." (PMID 26635512, 2015). "Thus, it was hypothesized that the inflammation due to adipose tissue expansion in obesity could be exacerbated by Nucb2 knockdown and lead to upregulation of HMGB1." (PMID 35406022, 2022). "Since nesfatin-1 ́s actions are preserved in conditions of leptin resistance, the present findings render the NUCB2/nesfatin-1 system an appealing target for the development of novel therapeutical treatments towards obesity." (PMID 32353862, 2020).
diabetes (35 papers, 2013 to 2026). "Las palabras clave de la búsqueda fueron “diabetes mellitus”, “diabetes”, “diabetes mellitus tipo 2”, “nesfatin-1”, “NUCB2”, “ELISA”, “plasma” y “suero”." (PMID 40865110, 2025). "The keywords used were “diabetes mellitus”, “diabetes”, “type 2 diabetes”, “nesfatin-1”, “NUCB2”, “ELISA”, “plasma”, and “serum”." (PMID 40865110, 2025). "Blood NUCB2/Nesfatin-1 levels in type 2 diabetes mellitus (DM) and gestational DM patients also seem to be lower." (PMID 31897389, 2019). "NUCB2 protein expression level was significantly decreased in the hypothalamus of Tsumura Suzuki obese diabetes mice compared with the control mice." (PMID 28533821, 2017). "Endogenous pancreatic islet nucleobindin 2 (NUCB2)/nesfatin is altered in diabetes and diet-induced obesity." (PMID 24330836, 2013). "Likewise, several studies indicate that NUCB2/Nesfatin-1 levels are lower in the patients with type 2 diabetes mellitus (DM), and gestational DM." (PMID 31897389, 2019). "Nesfatin-1, originating from its precursor protein called nucleobindin 2 (NUCB2), plays an important role in glucose metabolism and diabetes." (PMID 28533821, 2017).
Anxiety (29 papers, 2015 to 2026). Intense feelings of nervousness, tension, or panic often arise in response to interpersonal stresses. "In light of the proximity of the psychological constructs of depression and anxiety we also expected a positive association of NUCB2/nesfatin-1 and depression in the present study population." (PMID 26162003, 2015). "In the present study we evaluated the association between circulating NUCB2/nesfatin-1 and anxiety in anorexia nervosa." (PMID 26162003, 2015). "Longitudinal and interventional studies in different populations are needed in order to further investigate NUCB2/nesfatin-1’s implication in the regulation of anxiety and the causal direction of this interrelation." (PMID 26162003, 2015). "Since anxiety and depression are common comorbidities in AN, we investigated the association of NUCB2/nesfatin-1 with anxiety, depression and perceived stress in AN." (PMID 26162003, 2015). "Thus, this study aims at investigating the influence of rs757081 NUCB2 gene polymorphism in NB treatment response by evaluating changes in BMI, restraint, eating behaviours, depression, and anxiety in patients with OBE and BED." (PMID 38398053, 2024). "In humans, circulating NUCB2/nesfatin-1 has also been associated with increased levels of anxiety." (PMID 34502065, 2021). "Previous studies emphasized the predominant implication of NUCB2/NESF-1 in the mediation of anxiety in a sex-dependent manner." (PMID 38368491, 2024). "In recent years, nesfatin-1 [NESF-1; processed from nucleobindin-2/NUCB2] has received much attention due to its roles in metabolism, stress, and anxiety." (PMID 38368491, 2024). "NUCB2/nesfatin-1, an anorexigenic hormone that peripherally occurs in adipose tissue, was reported to be correlated with anxiety among anorectic as well as—in a sex-dependent manner—obese patients." (PMID 29261731, 2017). "Lastly, in a small sample we compared circulating NUCB2/nesfatin-1 levels of anorexia nervosa patients with normal weight patients matched for sex, age and anxiety scores." (PMID 26162003, 2015). "In a small sample we compared circulating NUCB2/nesfatin-1 levels of 10 anorexia nervosa patients with a sample of 10 normal weight subjects matched for sex, age and anxiety scores." (PMID 26162003, 2015). "Early on, the involvement of NUCB2/nesfatin-1 was also shown in the stress response of rodents and more recently also an implication of NUCB2/nesfatin-1 in the regulation of anxiety and depression in humans was described." (PMID 26162003, 2015). "Future studies with larger sample sizes are warranted to investigate possible differences in the regulation of NUCB2/nesfatin-1 with regards to anxiety, depression, perceived stress, and eating disorder symptoms in normal weight patients." (PMID 26162003, 2015). "This would suggest an inverse expression of central and peripheral NUCB2/nesfatin-1 in males and females under conditions of anxiety and depression which warrants further research to investigate this possible sex-specific effect." (PMID 26162003, 2015). "Homolog NUCB2 is a sex-specific correlate of depression, anxiety, and suicide in humans." (PMID 34035477, 2021). "As the main finding supporting the initial hypothesis we observed a significant correlation of NUCB2/nesfatin-1 with anxiety in a population of anorexic patients." (PMID 26162003, 2015). "NUCB2/nesfatin-1 might be primarily involved in the modulation of anxiety and subsequently in the regulation of eating habits and body weight in AN." (PMID 26162003, 2015). "Patients with high anxiety scores displayed 65% higher NUCB2/nesfatin-1 levels (p = 0.04)." (PMID 26162003, 2015). "The result of a positive association of NUCB2/nesfatin-1 with anxiety is in line with our previous finding in female obese patients showing higher levels of NUCB2/nesfatin-1 in subjects with increased anxiety which was also reflected in a strong correlation of NUCB2/nesfatin-1 with anxiety scores." (PMID 26162003, 2015).
Anxiety (continued). "It is important to acknowledge that multiple studies have shown the involvement of Nucb2/nesfatin-1 in anxiety- and depression-like behavior induction, and therefore Nucb2/nesfatin-1 may play a role in tumor-induced anorexia associated with CACS through variable pathways." (PMID 34073612, 2021). "In synopsis with the existing literature we therefore hypothesize that NUCB2/nesfatin-1 might be primarily involved in the mediation of anxiety and that its well-described influence on food intake and body weight is independent from disordered eating – at least in patients with anorexia nervosa." (PMID 26162003, 2015). "As hypothesized, we observed significantly higher NUCB2/nesfatin-1 plasma levels in female anorexic patients displaying high anxiety scores compared with those exhibiting low anxiety scores which resulted in a positive correlation of NUCB2/nesfatin-1 with anxiety scores." (PMID 26162003, 2015). "Additionally, elevated plasma levels of NUCB2/nesfatin-1 have been reported in female obese inpatients with high anxiety scores resulting in a correlation between NUCB2/nesfatin-1 and self-reported anxiety." (PMID 30513901, 2018). "Scores of PSQ-20 (73.3±14.3 vs. 48.6±17.2) and PHQ-9 (18.8±5.0 vs. 10.3±5.1) were higher in the high anxiety group (p<0.001) but did not correlate with NUCB2/nesfatin-1 (p>0.05)." (PMID 26162003, 2015). "In the present study, we therefore investigated the relationship between NUCB2/nesfatin-1 and different psychological parameters and hypothesized a positive correlation of NUCB2/nesfatin-1 primarily with anxiety which has been shown by our group in obese women before." (PMID 26162003, 2015). "However, it was not our main aim to compare NUCB2/nesfatin-1 levels of healthy controls with anorexic subjects but to investigate whether NUCB2/nesfatin-1 shows a positive correlation with anxiety also in female anorexic subjects." (PMID 26162003, 2015).
depression (29 papers, 2015 to 2026). "Circulating Nucb2 has been associated with panic disorder, reported depression, depression associated with subclinical hypothyroidism, and carcinogenesis and correlated with inflammatory markers such as IL-6 and C-reactive protein as well as corticosterone." (PMID 37386441, 2023). "We also expected positive associations of NUCB2/nesfatin-1 with depression and perceived stress as also shown for obese women in the same study." (PMID 26162003, 2015). "In addition, we recently described a positive association of NUCB2/nesfatin-1 with depression (measured by PHQ-9) in obese women." (PMID 26162003, 2015). "Another study depicted the sex-dependant regulation of NUCB2/NESF-1 under depressive conditions with the positive correlation of circulating NESF-1 with an increased degree of depression in obese female patients." (PMID 38368491, 2024). "A recent study described that circulating NUCB2/nesfatin-1 levels were significantly higher in patients with major depressive disorder compared to healthy controls." (PMID 30513901, 2018). "These significances were reached with positive correlations between NUCB2/nesfatin-1 and depression, perceived stress and eating disorder symptoms giving rise to a regulation of NUCB2/nesfatin-1 in a similar manner compared to anorexia nervosa." (PMID 26162003, 2015). "One study reported a positive correlation of plasma NUCB2/nesfatin-1 with depression (measured by Hamilton Depression Rating Scale, HAM-D) in a mixed-sex population of patients diagnosed with major depressive disorder and a healthy control group." (PMID 26162003, 2015). "First, we did not investigate NUCB2/nesfatin-1 in its association with nosological diagnoses as generalized anxiety disorder or major depressive disorder and did not provide a standardized diagnostic assessment." (PMID 26162003, 2015). "However, in the present population of female subjects with anorexia nervosa we did not observe a correlation of NUCB2/nesfatin-1 with depression as indicated by PHQ-9." (PMID 26162003, 2015).
type 2 diabetes mellitus (22 papers, 2013 to 2025). A type of diabetes mellitus that is characterized by insulin resistance or desensitization and increased blood glucose levels. "Our data with respect to NUCB2/Nesfatin-1 levels are similar to previous studies in which blood NUCB2/Nesfatin-1 levels were evaluated in PCOS patients and in the other cases of insulin resistance like type 2 diabetes, gestational diabetes or morbid obesity." (PMID 31897389, 2019).
Insulin resistance (21 papers, 2013 to 2026). Increased resistance towards insulin, that is, diminished effectiveness of insulin in reducing blood glucose levels. "Taken together, these data indicated that Nesf/NUCB2 was involved in the development of insulin resistance and fat deposition in the liver after HFD feeding and that these effects were independent of the modulation of energy intake." (PMID 26950482, 2016). "Although blood glucose levels were not different between Nesf/NUCB2-Tg mice and their non-Tg littermates fed 45% HFD, serum IRI level was significantly higher in Nesf/NUCB2-Tg mice than in their non-Tg littermates, indicating the development of insulin resistance in Nesf/NUCB2-Tg mice fed 45% HFD." (PMID 26950482, 2016). "The results of this study indicate that Nesf/NUCB2 was involved in the development of insulin resistance and fat deposition in the liver, independent of the modulation of energy intake." (PMID 26950482, 2016).